GSDME (gasdermin E)
Diseases named in the same sentence as GSDME in open-access papers (continued):
Sharing a sentence is not in itself a finding about the gene and the disease.
tumor (continued). "GSDME is a newly recognized executor of cellular pyroptosis, and has been recently implicated in tumor growth and immunity." (PMID 34901025, 2021). "GSDME-expressing tumors had more tumor-infiltrating immune cells, including NK cells, tumor-associated macrophages (TAMs) and CD8+ T lymphocytes, in comparison with control tumors." (PMID 33634141, 2021). "What is the effect of chemotherapeutic drugs on the tumor immune microenvironment by activating GSDME and causing pyroptosis in normal cells with high GSDME expression?" (PMID 33776057, 2021). "Pyroptosis-related genes (PRGs), such as NLRP3, Caspase 1 (CASP1), Gasdermin D (GSDMD) and Gasdermin E (GSDME), are strongly implicated in oncogenesis and tumor progression." (PMID 34488540, 2021). "In these cells, the overexpression of GSDME was found to convert apoptosis to pyroptosis and was associated with anti-tumor immune responses." (PMID 34490126, 2021). "Intriguingly, restoration of GSDME expression in cancer cells suppresses tumor growth mediated by enhancing the phagocytosis of tumor cells by tumor‐associated macrophages and the activation of tumor‐infiltrating natural killer (NK) and CD8+ T cells." (PMID 33179413, 2020). "The expression of GSDME enhances the phagocytic function of tumor-associated macrophages on tumor cells, and enhances the number and functions of tumor-infiltrating NK cells and CD8+ T cells." (PMID 33133646, 2020). "Treatment with the decitabine can induce the upregulation of DFNA5/GSDME expression in tumor cells, causing pyroptosis and making these cells more sensitive to chemotherapeutic drugs." (PMID 31501419, 2019). "Our results reveal that, in this tumor model, GSDME expression significantly associates with EMT." (PMID 41545335, 2026). "While GSDME is a tumor suppressor, it is also a cause of doxorubicin-induced cardiotoxicity." (PMID 41208882, 2025). "The expression of GSDME is precisely regulated through multi-layered molecular mechanisms, and its functional heterogeneity across different tumor types may be associated with dynamic interactions between epigenetic modifications and transcription factors." (PMID 40568597, 2025). "GSDME most likely has a tumor-suppressing function in cancers where GSDME is frequently mutated, while it has the opposite effect in cancer types with high endogenous expression of GSDME, such as GB." (PMID 40544161, 2025). "Although previous studies had revealed that Lenvatinib could induce GSDME-mediated pyroptosis, the underlying mechanisms and whether GSDME-mediated pyroptosis induced by lenvatinib can be used as an anti-tumor strategy remain unexplored." (PMID 40653759, 2025). "Hypermethylation of DFNA5 gene will cause GSDME absence in most tumor cells." (PMID 37984863, 2024). "USP48 facilitates pyroptosis by binding with GSDME, stripping its K48-linked ubiquitin, and thereby augmenting the functions of T cells and tumor-associated macrophages (TAMs) within the tumor microenvironment (TME), significantly boosting the efficacy of PD-1 inhibitors." (PMID 38702734, 2024). "GSDME, described as a genetic cause of hearing loss, has been considered as a tumor suppressor." (PMID 37134086, 2023). "Expression levels of GSDME were increased in a human cohort with oesophageal squamous cell carcinoma and associated with significantly better overall survival, hence acting as a tumor suppressor." (PMID 37664463, 2023). "In addition, GSDME expression is associated with the proliferation and function of tumor-associated CD4+ T cells, CD8+ T cells, TAMs, NK cells, etc50." (PMID 37705746, 2023). "Low expression of GSDME was associated with poor prognosis, suggesting that GSDME may act as a tumor suppressor in AML." (PMID 37679782, 2023). "Therefore, how to avoid this adverse effect caused by GSDME-mediated pyroptosis and provide tumor GSDME-specific targeted therapy is the focus of future research." (PMID 38104141, 2023).
tumor (continued). "GSDME expression enhanced the phagocytosis of tumor cells by tumor-associated macrophages and enhanced the number and function of tumor-infiltrating natural killer cells and CD8+ T cells, It can be cleaved by activated caspase-3 to produce its N-terminal fragment (GSDME-NT)." (PMID 35419279, 2022). "Moreover, it has been demonstrated that Gzm B directly cleaves GSDME to cause pyroptosis, which subsequently activates the immune system to protect against tumors and slow tumor growth." (PMID 36482419, 2022). "In addition, the loss of function is attributed to cancer-associated GSDME mutations, which further supports the perspective of GSDME as a tumor suppressor." (PMID 35462927, 2022). "It has been reported that GSDME-mediated pyroptosis promotes the development of colitis-associated colorectal cancer by releasing high-mobility group box protein 1, which induces tumor cell proliferation and the expression of proliferating nuclear antigen through the ERK1/2 pathway." (PMID 35673561, 2022). "In addition, natural killer cells induce the pyroptosis of GSDME-expressing tumour cells, and the underlying mechanisms are mediated by secreting granzyme B, which directly cleaves GSDME or activates caspase-3 to indirectly cleave GSDME." (PMID 35896522, 2022). "Next, we explored whether GSDME mediates PDAC resistance to pancreatic enzymatic digestion, thus explaining the tumour suppression induced by GSDME deficiency." (PMID 35292781, 2022). "GSDME deficiency in these models similarly suppressed tumour growth." (PMID 35292781, 2022). "Similarly, DFNA5 (gene encoding GSDME) was also overexpressed in tumors compared to non-tumor tissue." (PMID 35120582, 2022). "In addition, granzyme B from killer T cells directly cleaves gasdermin E and causes pyroptosis in tumor cells." (PMID 36038533, 2022). "In this study, we investigated whether CDK7 inhibition was an effective anti-tumor option and whether GSDME expression was associated with CDK7 levels." (PMID 34490348, 2021). "This may have important implications for cancer as numerous tumor cells were found to harbor loss-of-function mutations and/or reduced expression of GSDME suggesting a tumor suppressor function." (PMID 34490126, 2021). "Moreover, some tumors avoid GSDME-mediated tumor suppression through loss-of-function mutations, which surround the caspase-3 cleavage site to abolish GSDME-mediated tumor cytotoxicity." (PMID 34335940, 2021). "BRAF inhibitors together with MEK inhibitors could induce pyroptosis in melanoma with a higher HMGB1, more tumor-associated T cells, and less dendritic cell infiltration, while GSDME deficiency would reverse the anti-tumor immunity." (PMID 34298833, 2021). "Taken together, these results indicate that, besides the induction of GSDME-mediated pyroptosis, alteration of cancer progression-related genes by tetraarsenic hexoxide may be associated with the anti-tumor effects in TNBC cells." (PMID 33558527, 2021). "The mutations of tumor-associated GSDME also could inhibit pyroptosis." (PMID 39062587, 2024). "Our RNA-seq analysis revealed that GSDME increased cisplatin sensitivity and was closely associated with the cytokine-cytokine receptor interaction (ko04060) pathway, consistently indicating possible tumor immunity mediation by GSDME through the regulation of this pathway." (PMID 38169676, 2024). "In addition, GSDME-mediated pyroptosis of tumour cells enhances the it phagocytosis by tumour-associated macrophages, and triggers the recruitment of immune cells to induce anti-tumor inflammatory responses." (PMID 35662735, 2022). "In addition, overexpression of MUC1 or MUC13 rescued GSDME-deficiency-retarded tumour growth." (PMID 35292781, 2022). "Thus, LOF mutations together with the epigenetic suppression of GSDME might be two arch strategies developed by cancer cells to escape GSDME‐mediated tumor suppression." (PMID 34459122, 2021).
tumor (continued). "Given that activation of the tumor immune microenvironment is associated with immunotherapy efficacy and GSDME is highly expressed in TNBC (our data), polyI:C‐induced pyroptosis may provide more potent therapeutic efficacy than we expected for the treatment of TNBC." (PMID 33342034, 2021). "Importantly, tumor suppression effect of GSDME is abrogated in killer cytotoxic lymphocytes depleted mice or immune deficient mice, indicating tumor-suppressive function of GSDME requires pyroptosis-dependent activation of antitumor immunity." (PMID 33941231, 2021). "This induced tumor cell pyroptosis via the caspase-3/GSDME pathway, achieving a tumor inhibition rate of 96.1%." (PMID 41510161, 2026). "In this tumor, GSDME upregulation is correlated to epithelial-mesenchymal transition (EMT) and ETAR expression." (PMID 41545335, 2026). "IKBKE targeting reverses GEM resistance and enhances tumor immunogenic cell death via the caspase-3/GSDME pathway, supporting IKBKE inhibition as a promising therapeutic strategy for PDAC." (PMID 41699675, 2026). "GSDME activation can modulate infiltration of immune cells, including tumor‐associated macrophages (TAMs), through EIF2AK2, significantly improving anti‐tumor immunotherapy." (PMID 40783818, 2025). "Recent studies have highlighted that diverse small-molecule inhibitors can enhance therapeutic efficacy, tackle drug resistance and improve anti-tumor immunotherapy by activating the caspase-3/GSDME pathway-mediated pyroptosis." (PMID 40523886, 2025). "It has been shown that GSDME‐mediated pyroptosis not only kills tumor cells directly through cell death effect, but also indirectly enhances tumor immunosurveillance by promoting the infiltration of CD8+ T cells as well as the release of relevant cytokines." (PMID 41287826, 2025). "Secondly, GSDME directly promotes tumorigenesis; in vivo studies confirm that GSDME knockout markedly decreases tumor volume across multiple HCC models." (PMID 40568597, 2025). "The emerging evidence confirms that GSDME still maintains its tumor suppressor function in HCC under specific therapeutic conditions." (PMID 40568597, 2025). "Recent findings suggest that the mitochondria-mediated apoptotic pathway, involving ROS, can also trigger GSDME-dependent pyroptosis in some tumor cells." (PMID 41271670, 2025). "The authors demonstrated GSDME cleavage, a significant treatment effect, and activation of anti-tumor immunity." (PMID 40544161, 2025). "GSDME deficiency leads to reduced infiltration of CD8+ T cells, NK cells, and tumor-associated macrophages in the tumor microenvironment, significantly impairing antitumor immune responses." (PMID 40568597, 2025). "By analyzing the tumor growth curves, tumor volume, and tumor weight in each group, we found that for mice model with placebo treatment, overexpression of GSDME retarded the tumor growth and knockdown of GSDME promoted the tumor growth." (PMID 40653759, 2025). "In M-Cu-T, TAPP and Cu2+ synergistically generate massive ROS, causing mitochondrial dysfunction and activating the caspase-3/GSDME pathway to trigger tumor-specific immunogenic pyroptosis and initiate local anti-tumor immunity." (PMID 40717985, 2025). "Three PtIV prodrugs MRP, DRP, and HRP are designed to induce pyroptosis in low GSDME‐expressing tumor cells via the Caspase‐3/GSDME pathway." (PMID 40432601, 2025). "GSDME-mediated pyroptosis significantly increases tumor infiltration of CD8+ T cells by releasing IL-1β and IL-18, effectively reprogramming the immunosuppressive TME." (PMID 41267084, 2025). "Released RG108 reactivates the GSDME gene and reduces pyroptosis in low GSDME‐expressing tumor cells." (PMID 40432601, 2025). "In CAR-T therapy, granzyme B cleaves GSDME in tumor cells, which triggers macrophage activation of caspase-1/GSDMD and leads to IL-1β/IL-6 release." (PMID 41291696, 2025).
tumor (continued). "For mice model with Lenvatinib treatment, mice with GSDME overexpression exhibited slower tumor growth, suggesting that overexpression GSDME enhancing the therapeutic sensitivity of HCC to Lenvatinib." (PMID 40653759, 2025). "More recently, researchers discovered that GzmB directly cleaves GSDME, inducing pyroptosis and further activating the antitumor immune response, leading to the inhibition of tumor growth." (PMID 39316325, 2025). "Ionizing radiation can induce the development of pyroptosis in tumor cells by activating the intracellular Caspase‐9/Caspase‐3/GSDME pathway to induce pyroptosis in tumor cells." (PMID 41287826, 2025). "The up-regulation of GSDME induced by Tc3 explains why the anti-tumor activity of Tc3 was rescued after the knockdown of GSDME, even though the cell death mechanism shifted from pyroptosis to apoptosis." (PMID 39816682, 2025). "CAR-T cells release perforins to form pores that allow GZMB entry into the target tumor cells and caspase-3 activation, leading to GSDME cleavage and pyroptosis." (PMID 39917567, 2025). "The combination of DOX and JQ1 significantly triggered GSDME-dependent pyroptosis of tumor cells, further enhancing the number and function of tumor-infiltrating T lymphocytes." (PMID 40698137, 2025). "Studies have shown that IR can effectively initiate cell pyroptosis in tumor cell lines with high expression of GSDME, such as lung cancer, hepatocellular carcinoma, breast cancer, and glioma." (PMID 41287826, 2025). "A study demonstrated that GSDME acts as a tumor suppressor by activating pyroptosis and enhancing antitumor immunity." (PMID 40538398, 2025). "GSDME has a tumor-promoting role in GB by suppressing T cell infiltration and increasing tumor cell invasion." (PMID 40544161, 2025). "In cancer, GSDME‐mediated mitochondrial targeting and apoptosis‐to‐pyroptosis switch enhance immunogenic cell death, potentially influencing tumor suppression or immune evasion." (PMID 40783818, 2025). "For caspase-8, high expression of caspase-8 in the nucleus of tumor cells promotes tumor progression, while inhibits tumor growth by acting as a downstream of granzymes, specifically inducing GSDME cleavage." (PMID 40721869, 2025). "Overall, radiotherapy induces pyroptosis in high GSDME-expressing tumor cells, and hyperfractionated radiotherapy with specific chemotherapeutic agents potentially induces pyroptosis more extensively." (PMID 40765564, 2025). "This study aims to investigate the mechanisms by which fosinopril induces GSDME-mediated pyroptosis in tumor cells, with a focus on its anti-tumor effects in NSCLC, using both in vivo and in vitro models." (PMID 41271670, 2025). "Among all GSDMs, GSDME has the most well‐defined role in cancer and is the most extensively investigated in anti‐tumor therapies." (PMID 40783818, 2025). "Accumulating evidence has shown that chemotherapy and radiation act on GSDME to suppress tumor development." (PMID 41208882, 2025). "Collectively, these findings demonstrate that modulation of key signaling pathways can restore GSDME-dependent tumor suppression in HCC." (PMID 40568597, 2025). "This photodynamically triggered system initiates caspase-3/GSDME signaling and results in the controlled pyroptotic death of cancer cells, enabling precise spatial and temporal targeting in tumor therapy." (PMID 40806716, 2025). "Targeting GSDME to modulate the pyroptosis response is an extremely promising pathway in tumor therapy." (PMID 41267084, 2025). "Pyroptosis is dependent on the cleavage and activation of Gasdermin protein family members, and in particular, the role of Gasdermin E in tumor cells has received increasing attention." (PMID 41287826, 2025). "In melanocytomas, triggering GSDME-induced pyroptosis inhibited tumor growth and increased GSDME expression increased the sensitivity of melanocytomas to etoposide." (PMID 40756987, 2025).
tumor (continued). "Gasdermin E (GSDME), a key executor of pyroptosis, exerts a unique dual role in tumorigenesis, acting as both a tumor suppressor and a tumor-promoting factor." (PMID 40568597, 2025). "In BRAF inhibitor-resistant melanoma cells, small molecules such as the Caspase-3 agonist raptinal reversed the resistant phenotype by restoring GSDME expression, significantly enhancing tumor cell sensitivity to chemotherapeutic agents." (PMID 40497999, 2025). "USP48, by stabilizing Gasdermin E (GSDME), promotes pyroptosis and enhances the therapeutic efficacy of programmed cell death protein 1 inhibitors in mouse tumor models." (PMID 40607251, 2025). "In the present study, we have demonstrated for the first time that FBZ inhibits the tumor glycolysis-induced caspase-3/GSDME pathway for pyroptosis in EMT6 cells." (PMID 40756987, 2025). "First and foremost, the activation of GSDME significantly promotes the infiltration of immune cells into the tumor microenvironment through the release of inflammatory cytokines, such as IL-1β and IL-18." (PMID 40568597, 2025). "Recent studies have demonstrated that GSDME plays a crucial role in the mechanism of tumor cell death induced by chemotherapy." (PMID 40256765, 2025). "Additional advantageous VSV features include the ability to replicate in the hypoxic tumor microenvironment (TME) and induce tumor cell pyroptosis via activation of the caspase-3/gasdermin E (GSDME) axis with an anti-tumor response." (PMID 40943484, 2025). "Nonetheless, recent studies have shown that GSDME is of great importance on the mechanism of tumor cells death induced by chemotherapy." (PMID 40256765, 2025). "In experimental models, the combination of AZD5438 and PD0325901 not only outperformed either monotherapy in suppressing tumor growth but also augmented CD8+ T cell-mediated antitumor immunity by promoting caspase-8/gasdermin E-dependent pyroptosis." (PMID 41194215, 2025). "Ca2+ induces tumor cell pyroptosis primarily through the GSDME pathway, whereas Zn2+ induces tumor cell pyroptosis primarily through the GSDMD pathway." (PMID 40486836, 2025). "GSDME plays an important part in increasing the anti-tumor functions of tumor-infiltrating NK and CD8+ T cells, offering new inspiration for pyroptosis-mediated cancer treatments." (PMID 39816682, 2025). "Consistent with the induction of pyroptosis observed in vitro, western blot analysis confirmed increased expression of GSDME in tumor tissues from H62-treated mice." (PMID 41239499, 2025). "What makes this particularly intriguing is that GSDME appears to promote tumor growth in HCC, contrasting sharply with its tumor-suppressing role in other cancers." (PMID 40568597, 2025). "GSDME is a key protein in the switch between apoptosis and cellular pyroptosis and has been identified as a potential tumor suppressor gene." (PMID 40756987, 2025). "GSDME serves as a switch molecule in the transformation of apoptosis and pyroptosis, and its expression level determines the mode of tumor cell death." (PMID 40256765, 2025). "The inhibitory effect of DHN was closely associated with GSDME cleavage and the formation of punctate structures of STING in tumor tissues." (PMID 40663398, 2025). "In vivo experiments have confirmed that BI2536 not only induces pyroptosis through the caspase‐3/GSDME pathway but also increases CD8+ T‐cell infiltration in tumor sites." (PMID 39994841, 2025). "TMAO activates the endoplasmic reticulum (ER) stress kinase PERK, triggers gasdermin E-mediated tumor cell pyroptosis, and boosts CD8 + T cell-mediated anti-tumor immunity in vivo in triple-negative breast cancer." (PMID 41311499, 2025). "Research indicates that GSDME plays a crucial part in sensitizing tumor cells to poly (ADP-ribose) polymerase inhibitors (PARPi), suggesting a potential avenue to enhance therapeutic efficacy in resistant cancers." (PMID 41291696, 2025).